TJP1 (tight junction protein 1)
Diseases named in the same sentence as TJP1 in open-access papers (continued):
Sharing a sentence is not in itself a finding about the gene and the disease.
gastric cancer (11 papers, 2020 to 2025). A primary or metastatic malignant neoplasm involving the stomach. "Their findings suggest that TJP1 plays a significant role in gastric cancer development, highlighting the intricate relationship between H. pylori-induced alterations in tight junctions and the progression of gastric carcinogenesis." (PMID 40654572, 2025). "Studies conducted by Choi and colleagues have investigated the expression levels of TJP1 in H. pylori-positive gastric cancer patients and post-H." (PMID 40654572, 2025). "Taken together, our results indicated that circSMC3/miR‐4720‐3p/TJP1 axis gave us a new direction for the potential treatment of gastric cancer." (PMID 32314520, 2020). "The levels of TJP1 in gastric cancer tissues (stomach adenocarcinoma) are higher than normal tissues based on the GEPIA database." (PMID 32314520, 2020). "This research characterized the regulation of circSMC3/miR‐4720‐3p/TJP1 axis and its role in gastric cancer." (PMID 32314520, 2020). "Taken together, our study identified the role of circSMC3 in gastric cancer cells via sponging miR‐4720‐3p to initiate TJP1 potential." (PMID 32314520, 2020). "Thus, our results indicate that circSMC3 promotes gastric cancer cell proliferation and motility through miR‐4720‐3p/TJP1." (PMID 32314520, 2020). "It was reported that TJP1 could promote gastric cancer cell proliferation and motility." (PMID 34485273, 2021). "Furthermore, miR‐4720‐3p and TJP1 also affected gastric cancer cell growth and motility." (PMID 32314520, 2020).
cervical cancer (9 papers, 2021 to 2025). A primary or metastatic malignant neoplasm involving the cervix. "Conversely, expression of the epithelial markers E-cadherin (CDH1) and ZO-1 (TJP1) was increased, suggesting that JNK/c-Jun activity is required for the invasive potential of cervical cancer cells, potentially through the regulation of EMT-associated proteins." (PMID 33303976, 2021).
bladder cancer (8 papers, 2021 to 2025). "In our data showed expression of TJP1 protein was associated with grade and stage in patients with bladder cancer." (PMID 35087173, 2022). "It was found that high TJP1 expression levels in bladder cancer tissues were significantly associated with age (p = 0.03), grade (p = 0.007), and stage (p = 0.011)." (PMID 35087173, 2022). "Knockdown of TJP1 inhibits cell proliferation, migration, and invasion in bladder cancer cell lines, while, TJP1 mRNA expression is associated with lymph node metastasis in bladder cancer patients." (PMID 35087173, 2022). "Further mechanisms are needed to investigate the underlying TJP1 expression and subsequently increased chemosensitivity in bladder cancer." (PMID 35087173, 2022). "Taken together, TJP1 expression is associated with poor clinical outcomes in patients with bladder cancer and can be a useful predictive biomarker for bladder cancer staging." (PMID 35087173, 2022). "Another tight junction protein, TJP1, was also reported to promote vasculature remodelling in bladder cancer." (PMID 35224833, 2022). "The genetic alterations of the TJP family in bladder cancer, examined using cBioPortal, showed that the genetically altered ratios of TJP1, TJP2, and TJP3 were 3%, 3%, and 1.7%, respectively." (PMID 35087173, 2022). "A previous study showed that TJP1 expression is correlated with cell motility in bladder cancer cells." (PMID 35087173, 2022). "We found that TJP1 was amplified in bladder cancer tissue and that the protein expression levels were significantly associated with age (p = 0.03), grade (p = 0.007), and stage (p = 0.011)." (PMID 35087173, 2022). "TJP1 and TJP3 had a 2.5–4% amplification ratio and TJP2 has a 5% mutation ratio in bladder cancer patients." (PMID 35087173, 2022). "The results also showed that TJP1 was significantly upregulated in the urothelial carcinoma group in bladder cancer specimens compared to normal bladder tissues." (PMID 35087173, 2022). "TJP1 protein expression correlated to tumor grade and stage, indicating that TJP1 can be used as an independent biomarker for bladder cancer staging." (PMID 35087173, 2022). "IHC staining results show that TJP1 was significantly upregulated in bladder cancer specimens compared to normal bladder tissues." (PMID 35087173, 2022). "Moreover, studies on metastasis and tight junction proteins have demonstrated that the expression of TJP1 mRNA is correlated with lymph node metastasis in patients with human bladder cancer." (PMID 38255907, 2024). "In this context, knockdown of the tight junction protein 1 (TJP1) gene expression significantly decreased bladder cancer cells’ growth, via dysfunction of the miR-455-TJP1 axis, where the latter suppressed TJP1 expression by directly targeting its 3′-untranslated region." (PMID 36672179, 2023). "TJP1 genetic amplification was correlated with mRNA expression in patients with bladder cancer." (PMID 35087173, 2022). "In this study, we investigated whether the ZO family (TJP ZO1, ZO-2, and ZO-3, encoded by the TJP1, TJP2, and TJP3 genes, respectively) is associated with the malignant phenotype in bladder cancer." (PMID 35087173, 2022). "Specifically, high TJP1 mRNA expression has been reported in patients with bladder cancer." (PMID 35087173, 2022). "The results showed TJP1 protein was upregulated in bladder cancer cells." (PMID 35087173, 2022). "Therefore, in this study, we focused on TJP1 for further investigation of bladder cancer." (PMID 35087173, 2022). "Moreover, we further evaluated expression of TJP1 protein in bladder cancer cell lines." (PMID 35087173, 2022). "The results showed that TJP1 mRNA levels were positively correlated with TTN and RYR3 mRNA levels in bladder cancer tissues." (PMID 35087173, 2022).
bladder cancer (continued). "TJP1 mRNA levels were positively correlated with TTN and RYR3 mRNA levels in bladder cancer tissue." (PMID 35087173, 2022). "In addition, TJP1 mRNA expression levels were positively correlated with TNT and RYR3 mRNA expression levels in patients with bladder cancer." (PMID 35087173, 2022). "However, TJP1 mRNA expression was not significantly correlated with chemotherapy in bladder cancer cell lines." (PMID 35087173, 2022). "We could not exclude the possibility that TJP1 amplification or expression is correlated with the response rate to immune checkpoint blockade; however, this is the first study to evaluate the TJP1 genetic alterations in bladder cancer patients." (PMID 35087173, 2022). "While analyzing the frequency of the co-occurrence of genetically altered TJP1–3 in the same specimen, it was found that genetic alterations of the other TJP family members were not significant in bladder cancer patients." (PMID 35087173, 2022).
Insulin resistance (7 papers, 2020 to 2025). Increased resistance towards insulin, that is, diminished effectiveness of insulin in reducing blood glucose levels. "Despite improved adipose tissue inflammation and overrepresentation of A. muciniphila and P. goldsteinii, PEG400 administration failed to improve insulin resistance by upregulating Tjp1, which encodes the tight junction protein ZO-1 and is implicated in gut barrier function." (PMID 37630442, 2023).
C. perfringens infection (6 papers, 2018 to 2022). "C. perfringens infection reduced the expressions of CLDN1 and TJP1, whereas the CF extract with or without butyrate tended to reverse the trend and enhanced both gene expressions." (PMID 35139922, 2022).
Cirrhosis (6 papers, 2020 to 2024). A chronic disorder of the liver in which liver tissue becomes scarred and is partially replaced by regenerative nodules and fibrotic tissue resulting in loss of liver function. "The expression of TJP1 gene was significantly reduced in patients with decompensated cirrhosis compared to compensated cirrhosis (p < 0.05)." (PMID 37304826, 2023).
depression (6 papers, 2019 to 2024). "Depression was also negatively correlated to TJP1, and positively correlated to enteroendocrine protein CGB, and positively correlated to satiety." (PMID 33750831, 2021). "Another study also confirmed increased transcription of TJP1/ZO-1 and CTNNA1 in the dACC of suicidal patients with depression compared to psychiatrically normal controls." (PMID 38891940, 2024).
liver fibrosis (6 papers, 2020 to 2025). "We also observed a decrease in the expression of the tight junction proteins ZO-1 (Tjp1) and Esam in LyECs after liver fibrosis, which indicated that the permeability of hepatic LyECs was affected." (PMID 36632228, 2023). "Our transcriptome sequencing results also showed decreased Prox1 expression in LyECs from liver fibrosis mice, and the expression of the tight junction proteins ZO-1 (Tjp1) and Esam in LyECs was downregulated after liver fibrosis, which indicated that the permeability of hepatic LyECs was affected." (PMID 36632228, 2023).
ovarian carcinoma (6 papers, 2014 to 2025). A malignant neoplasm originating from the surface ovarian epithelium. "In this study, we used CRISPR-Cas9-mediated gene editing to generate TJP1 knockout (KO) ovarian cancer cell lines and investigated the impact of ZO-1 loss on the expression of angiogenesis-related genes." (PMID 40943311, 2025). "Two epithelial ovarian cancer cell lines, SKOV3 and OVCAR3, were transfected with plasmids encoding Cas9 and guide RNAs (gRNAs) specifically targeting the ZO-1 gene (TJP1)." (PMID 40943311, 2025). "In this study, we aim to elucidate the role of TJP1 (ZO-1) in regulating tumor angiogenesis in ovarian cancer." (PMID 40943311, 2025).
atopic dermatitis (5 papers, 2018 to 2024). "At the mRNA level, calcitriol enhanced the expression of claudin-1, occludin, and tight junction protein 1 (Tjp1, gene encoding ZO-1) in NC/Nga mice with atopic dermatitis." (PMID 37298299, 2023). "Interestingly, calcitriol application upregulated filaggrin, loricrin, claudin-1, and Tjp1 in NC/Nga mice with atopic dermatitis." (PMID 37298299, 2023). "In patients with atopic dermatitis, it has been reported that the mRNA expression of filaggrin, loricrin, occludin, and claudin-1 was decreased, while the expression of involucrin and TJP1 was not affected compared with control subjects." (PMID 37298299, 2023). "At the mRNA level, involucrin and occludin were downregulated, while the expression of filaggrin, loricrin, claudin-1, and Tjp1 was not changed in NC/Nga mice with atopic dermatitis." (PMID 37298299, 2023).
cerebral malaria (5 papers, 2009 to 2024). A sequestration of Plasmodium falciparum in the brain, which can cause coma and/or seizures. "This key step in cerebral malaria occurs via alterations in the expression levels of tight junction proteins, such as occludin (OCLN) and ZO-1 (also known as TJP1)." (PMID 35815443, 2022).
glomerulosclerosis (5 papers, 2014 to 2022). A hardening of the kidney glomerulus caused by scarring of the blood vessels. "Taken together, these data provided evidence that Tjp1 is indispensable for the maintenance of glomerular structure and function and that the elimination of Tjp1 leads to global glomerulosclerosis." (PMID 25184792, 2014).
lung disease (5 papers, 2020 to 2025). "The remaining 11 genes in the region encode proteins associated with neurologic disorders (APBA2, CHRFAM7A, MTMR10, FAN1), skin and eye pigmentation or development (OCA2, HERC2, TJP1, TRPM1), nephritis (ARHGAP11B, MTMR10, FAN1), and lung disease (ENTREP2, NSMCE3)." (PMID 40013929, 2025).
cholestasis (4 papers, 2021 to 2025). Impairment of the bile flow caused by obstruction within the liver, or outside the liver in the bile duct system. "In particular, USP53 contributes to the maintenance of tight junction integrity through interactions with TJP1 and TJP2, and its loss leads to canalicular membrane instability and cholestasis." (PMID 41356217, 2025).
leukemia (4 papers, 2011 to 2020). A malignant (clonal) hematologic disorder, involving hematopoietic stem cells and characterized by the presence of primitive or atypical myeloid or lymphoid cells in the bone marrow and the blood. "This region harbors the leukemia-related gene TJP1 (ZO-1), which encodes a protein involved in signal transduction at cell-cell junctions." (PMID 26872047, 2016). "This status is closely correlated with the pathogenesis and progression of the disease, so the TJP1 (ZO-1) gene has been proposed as being a clinical molecular marker of leukemia." (PMID 26872047, 2016). "Although TJP1 (ZO-1) deletions are infrequent in leukemia, previously have detected the hypermethylated status of TJP1 (ZO-1) gene promoter region in newly diagnosed acute leukemia and relapse disease patients." (PMID 26872047, 2016).
multiple myeloma (4 papers, 2016 to 2021). "In particular, high TJP1 expression in myeloma plasma cells was associated with a better and longer response to protease inhibitors (PI), suggesting this gene as a biomarker in order to identify patients who can benefit from PI-based therapy." (PMID 33921415, 2021). "Of relevance in this regard, a recent study by Orlowski and colleagues identified low levels of TJP1 encoding the epithelial marker tight junction protein 1 (also known as zonula occludens 1) as a determinant of myeloma proteasome inhibitor resistance." (PMID 27626179, 2016). "Tight junction protein 1 (TJP1) has recently been proposed as a biomarker to identify multiple myeloma (MM) patients most likely to respond to bortezomib- and carfilzomib-based proteasome inhibitor regimens." (PMID 28966941, 2017).
nasopharyngeal carcinoma (4 papers, 2019 to 2025). A carcinoma arising from the nasopharyngeal epithelium. "Circ-CCNB1 inhibits migration and invasion of nasopharyngeal carcinoma by promoting binding between NF90 and TJP1 mRNA, stabilizing TJP1 mRNA, and enhancing tight junctions between tumor cells." (PMID 36358938, 2022).
co-infection (3 papers, 2020 to 2025). "As representative protein components of the intra- and intercellular tight junction complex, we choose zona occludens 1 (Zo-1/Tjp1) and occludin (Ocln) and evaluated by IFA whether infection with the parasites alone or in co-infection lead to alterations in barrier integrity." (PMID 33692963, 2020).
cryptorchidism (3 papers, 2024 to 2025). The failure of one or both testes of a male fetus to descend from the abdomen into the scrotum during the late part of pregnancy. "It was found that the mRNA and protein levels of ZO-1, also known as tight junction protein 1 (TJP1) in yak, and β-catenin were both significantly reduced in cryptorchidism (p < 0.01)." (PMID 39120333, 2024).
glomerular diseases (3 papers, 2014 to 2025). "We had previously demonstrated that the constitutive inactivation of Tjp1 in mice resulted in an early embryonic lethality; thus, it was unlikely that Tjp1 was actually mutated in congenital human glomerular diseases." (PMID 25184792, 2014). "The several previous studies have indicated that tight junctions and Tjp1 are implicated in glomerular disorders." (PMID 25184792, 2014). "To investigate whether the kidney disorder caused by the podocyte-specific Tjp1 inactivation had a similarity with human glomerular diseases, we performed pathological analyses that have been commonly utilized in the diagnosis of human renal disease." (PMID 25184792, 2014). "Together with previous findings that Tjp1 expression was decreased in glomerular diseases in human and animal models, our results indicate that the suppression of Tjp1 could directly aggravate glomerular disorders, highlights Tjp1 as a potential therapeutic target." (PMID 25184792, 2014).
ileitis (3 papers, 2024 to 2025). "Curdlan-induced goblet cell loss and ileitis occur after P.g. or L.m. monoassociation, even though L.m. has greater capacity than P.g. to stimulate low levels of Il23a, Grp78, Tjp1, mucin, and ZO-1 in naive mice." (PMID 40762957, 2025).
leiomyosarcoma (3 papers, 2021 to 2024). An uncommon, aggressive malignant smooth muscle neoplasm, usually occurring in post-menopausal women. "TJP1 acts in two signaling pathways related to adherent unions and gap junctions and contributes to cell proliferation in leiomyosarcoma by favoring cell–cell aggregation and cytokine-mediated communication in the tumor microenvironment." (PMID 38994952, 2024). "Notably, in leiomyosarcoma, TJP1 knockdown led to the activation of multiple signaling pathways, including the NF-κB pathway and growth factor receptor signaling, resulting in enhanced tumor growth because of CSF1 and CTLA4 expression." (PMID 37790849, 2023). "Targeting TJP1 could attenuate cell–cell aggregation and enhance chemosensitivity to doxorubicin in leiomyosarcoma." (PMID 34485273, 2021).
ulcer (3 papers, 2025). "Moreover, sodium butyrate promoted the mRNA and protein expressions of tight junction protein-1 (ZO-1) and Claudin-1 in the epithelial cells of the ulcer tissue." (PMID 40818135, 2025).
Atrophy (2 papers, 2024 to 2025). Any weakening or degeneration, especially through lack of use. "Urinary miR-185-5p, a non-invasive biomarker of tubular atrophy/interstitial fibrosis in IgAN, may promote the transformation of renal tubular epithelial cells to a fibrotic phenotype via TJP1." (PMID 38426107, 2024).
gastric tumor (2 papers, 2020 to 2023). "The expression of ACTA2, HIF1A, and VEGFA was independently associated with TJP1 in non-cancerous tissue, explaining 90% in its variability, and BCL2, HIF1A, CDKN1A, and PTGS2 were independently associated with TJP1 in gastric tumors, explaining 98% in gene variability." (PMID 32630408, 2020).
mental disorder (2 papers, 2019 to 2020). A disease that has its basis in the disruption of mental process. "Correlation analysis revealed that there was a consistent and robust negative correlation between the expression of tight junction mRNAs and the duration of psychiatric disease with longer duration of disease associated with reduced expression of CLDN12 and TJP1 notably." (PMID 33139732, 2020).
renal cell carcinoma (2 papers, 2023). "Overall, this study contributes to the growing body of knowledge on autophagy in renal cell carcinoma and underscores the significance of TJP1 in modulating autophagy and its potential as a prognostic biomarker." (PMID 37790849, 2023).
schizophrenia (2 papers, 2017 to 2020). A major psychotic disorder characterized by abnormalities in the perception or expression of reality. "Former evidences demonstrated a strong association of GJD2 and TJP1 with schizophrenia." (PMID 29020091, 2017).
vitamin A deficiency (2 papers, 2019 to 2021). Deficiency of vitamin A due to malnutrition, malabsorption, or dietary lack. "Vitamin A deficiency decreased the mRNA levels of TJ complexes (several cldns and tjp1) in grass carp (Ctenopharyngodon idella), dietary isoleucine decreased the expression of several cldns in Jian carp (Cyprinus carpio var." (PMID 31619276, 2019).
Wilms tumor (2 papers, 2021 to 2022). An embryonal neoplasm characterized by the presence of epithelial, mesenchymal, and blastema components. "For example, circCDYL sponges miR-145-5p to augment tumor-suppressor TJP1 in Wilm’s tumor." (PMID 36058922, 2022). "The expression level of TJP1 in Wilms’ tumor cells was identified via Western blot." (PMID 34485273, 2021).
esophageal tumors (1 paper, 2020). "In addition, epithelial marker TJP1 tended to be decreased in esophageal tumors as well." (PMID 32630408, 2020).
Infertility (1 paper, 2017). "Similar results were obtained in rabbits fed with cholesterol‐rich diet in which the disruption of the BTB and the appearance of unconventional TJP1 in endosomes were correlated with impaired spermatogenesis and infertility." (PMID 28244681, 2017).
Intellectual disability (1 paper, 2017). "Genes APBA2, NDNL2 and TJP1 that are triplicated in case VI may be responsible for the more severe intellectual disability." (PMID 28174603, 2017).